ENSG00000287246 (novel transcript)
Gene: Long non-coding RNA gene on chromosome 10 (4,437,102 to 4,515,244, forward strand). Ensembl gene ENSG00000287246.
Gene Ontology:
Molecular function: U4 snRNA binding
Biological process: formation of quadruple SL/U4/U5/U6 snRNP; spliceosomal tri-snRNP complex assembly
Cellular component: U4/U6 x U5 tri-snRNP complex; U6 snRNP